PHGDH (phosphoglycerate dehydrogenase)
Diseases named in the same sentence as PHGDH in open-access papers (continued):
Sharing a sentence is not in itself a finding about the gene and the disease.
glioma (continued). "Inhibition of PHGDH expression in glioma cells downregulated the expression of VEGF, MMP-2, CHK2 and cyclin D1 and reduced glioma cell proliferation, invasion and tumorigenicity in vitro and in vivo." (PMID 23229761, 2013). "PHGDH expression was also higher in GSCs and tumor cells derived from GBM samples compared to neural progenitor cells (NPCs), normal human astrocytes (NHAs), and conventional glioma cell lines." (PMID 40102981, 2025). "Recent studies indicate that PHGDH expression is reduced by 40-50% in 1p/19q-codeleted gliomas compared to non-codeleted gliomas, suggesting these gliomas have selective vulnerability to serine and glutathione depletion." (PMID 40265021, 2025). "PHGDH was also recently reported to have a non-metabolic role in glioma tumorigenesis via stabilization of the transcription factor FOXM1." (PMID 32477466, 2020). "The expression of PHGDH (mRNA and protein), which is absent in normal brain tissue, was increased in gliomas as a direct function of tumor grade, with more aggressive tumors expressing higher levels of this protein." (PMID 32477466, 2020). "We analyzed PHGDH levels in specimens from glioma patients and found that PHGDH, although negative in normal brain tissues, was highly expressed in astrocytic tumors and increasingly expressed in more aggressive cancer types." (PMID 23229761, 2013). "Our data identified PHGDH as a potential prognostic marker of glial brain tumors and identified a non-metabolic role for PHGDH in glioma tumorigenesis, providing a novel angle of targeting the PHGDH–FOXM1 axis in future brain tumor therapy." (PMID 23229761, 2013). "However, the specific mechanism by which PHGDH regulates glioma angiogenesis has not yet been reported." (PMID 37187454, 2023). "Analysis of PHGDH levels in specimens from glioma patients revealed that although PHGDH is not normally expressed in healthy brain tissue, significant elevations were observed in astrocytic tumors in increasing correlation with progressively advanced tumor grade." (PMID 25574168, 2014). "However, PHGDH expression in glioma and a potential non-metabolic role in tumorigenesis have not been reported." (PMID 23229761, 2013). "Further studies showed that PHGDH interacts with N-terminal of FOXM1, stabilized FOXM1 from ubiqutintion induced protesome degradation in glioma cells, suggesting that PHGDH may be a regulator of FOXM1, and that PHGDH has additional biological functions in addition to those as a metabolic enzyme." (PMID 23229761, 2013). "However, the expression of PHGDH in glioma and its roles in addition to the Warburg effect has not yet been demonstrated." (PMID 23229761, 2013). "This phenomenon was attributed to the lower expression of PHGDH and CTH, enzymes involved in serine and cystathionine metabolism, in gliomas with chromosomal alterations compared to those without them." (PMID 39996200, 2025).
lung carcinoma (31 papers, 2011 to 2026). "In lung cancer, serine synthesis gene expression is variable, yet, expression of the initial enzyme, phosphoglycerate dehydrogenase (PHGDH), was found to be associated with poor prognosis." (PMID 38515202, 2024). "In A549 human lung cancer cells, PHGDH (phosphoglycerate dehydrogenase) promoted Cd-induced autophagy, as well as Cd increased PHGDH expressions." (PMID 40806643, 2025). "One recent study shows that the high expression of PHGDH is closely related to the low expression of Parkin in both breast and lung cancers." (PMID 39207107, 2024). "Four lung cancer cell lines, A549, H1299, H460 and H358 showed robust PHGDH expression, and two of them, A549 and H460, in fact harbour a KEAP1 mutation." (PMID 38515202, 2024). "Remarkably, PHGDH expression is significantly upregulated in a variety of cancers, including colorectal, gastric, bladder, breast, and lung cancers (15, –, 19)." (PMID 39207107, 2024). "High PHGDH expression has also been reported as a poor prognostic factor in patients with advanced or recurrent non‐small cell lung cancer treated with anti‐PD‐1/PD‐L1 antibodies, which would suggest that PHGDH inhibitors have potential clinical application." (PMID 38874588, 2024). "PHGDH is also a high-expression proto-oncogene in lung cancer that promotes cancer progression by activating serine synthesis." (PMID 36699468, 2022). "NCT503 was identified from the National Institutes of Health (NIH) Molecular Libraries Small Molecule Repository (MLSMR) drug library as a specific inhibitor of PHGDH; it inhibited the malignant phenotype in breast, liver, and lung cancers in a PHGDH-dependent manner." (PMID 37223471, 2023). "It is often downregulated in many types of cancer, PHGDH is a ubiquitinated protein of Parkin and interacts directly with Parkin at its Lys-330, and the degradation of PHGDH mediated by Parkin blocks serine synthesis in breast and lung cancer." (PMID 37190313, 2023). "Consequently, low expression of Parkin in lung cancer contributes to the high expression of PHGDH." (PMID 36699468, 2022). "In this study, we identify key enzymes in the serine synthesis pathway (SSP), namely PHGDH, PSAT1 and PSPH, as well as the serine transporter SLC1A4, which are significantly overexpressed in lung cancer and correlate with poor patient prognosis." (PMID 41702885, 2026). "Molecular docking was employed to explore the binding affinity between the most active compounds (7a and 7g) and two key enzymes, PHGDH and PSAT1, which play vital roles in the progression of lung cancer." (PMID 40013064, 2025). "Our analysis of Kaplan–Meier plots derived from data on 1925 lung cancer patients clearly confirmed the strong oncogenic role of HK2, LDHA, PHGDH, PSAT1, SHMT2, MTHFD2, c-Myc, and ATF4 (CREB-2) in lung cancer." (PMID 37233697, 2023). "Elevation of key SSP enzymes, such as PHGDH, PSAT1, and PSPH, is an important factor in the malignant progression of lung cancer cells and cancer drug resistance." (PMID 36699468, 2022). "All data together indicated that the downregulation of c-Myc, HK2, PKM2, LDHA, PHGDH, PSAT1, cyclin D1, and CDK6 in lung cancer cells was related to the ubiquitin-protein degradation pathway, which was the result that the USP28 was inhibited by SGH." (PMID 33572615, 2021). "However analyzing patient datasets of lung cancer our analysis reveled that some other enzymes of the pathways, rather than PHGDH, might be associated to prognosis." (PMID 25436979, 2014). "Molecular docking was employed to explore the potential interactions between the most active compounds (7a and 7g) and two key enzymes, human 3-phosphoglycerate dehydrogenase (PHGDH) and phosphoserine aminotransferase (PSAT1), which play vital roles in the progression of lung cancer." (PMID 40013064, 2025).
lung carcinoma (continued). "The increased expression of phosphoglycerate dehydrogenase (PHGDH) and the upregulation of both phosphoserine aminotransferase 1 (PSAT1) and phosphoserine phosphatase (PSPH) highlight the importance of the serine biosynthesis pathway in lung cancer biology." (PMID 31803611, 2019). "However, PHGDH did not appear to have any prognostic value in lung cancer datasets, whereas is some datasets PSAT-1, PSPH or SHMT-2 were able to predict patient survival." (PMID 25436979, 2014). "However, the increased expression of the PHGDH mRNA did not appear to have any prognostic value in seven analyzed lung cancer datasets, highlighting the importance of the cell-specific molecular background as the key determinant for activating specific signaling pathways." (PMID 30857125, 2019). "There is also a study showing the increased protein level of all three proteins (fold change: PHGDH: +3.62; PSAT 1: +6.94: PSPH: +1.27) in lung cancer tissue, when compared to corresponding non-tumorous tissue." (PMID 37376060, 2023). "Additionally, we also want to know if PLK1 OE in other cancer cell type leads to the decrease of PHGDH, so we overexpressed PLK1 in lung cancer cell line A549 and found the decrease of PHGDH and no change of PSAT1." (PMID 40475404, 2025).
colorectal cancer (26 papers, 2019 to 2026). A primary or metastatic malignant neoplasm that affects the colon or rectum. "Scaffolding functions include eIF4A1/eIF4E binding in pancreatic cancer to enhance oncoprotein translation, while the circMYBL2-encoded p185 promotes UCHL3-mediated PHGDH degradation to inhibit colorectal cancer invasion." (PMID 41486146, 2026). "In gliomas and cervical, pancreatic, and colorectal cancer, the overexpression of PHGDH is associated with advanced TNM stage, large tumor, higher tumor grade, and shorter overall survival time, respectively." (PMID 39670663, 2025). "Subsequently, circMYBL2-encoded p185 counteracts this stabilization, suppressing PHGDH-mediated serine synthesis to inhibit colorectal cancer progression and aggressiveness." (PMID 40598535, 2025). "Pro-Metastatic Functions of High PHGDH Expression: Transcriptional upregulation by MYC in colorectal cancer." (PMID 41486146, 2026). "DDB1 increases poly-ubiquitination and degradation of PHGDH, inhibiting colorectal cancer growth and stemness via an enzyme-independent mechanism." (PMID 40598535, 2025). "Previously, we demonstrated that high Serine (Ser) availability, obtained by increased exogenous uptake or increased PHGDH expression, supports 5-Fluorouracil (5-FU) resistance in colorectal cancer (CRC)." (PMID 40640948, 2025). "Compared with previous findings in colorectal cancer cells, lipid metabolism, amino acid metabolism, and purine metabolism were also enriched in colon cancer organoids with high PHGDH expression." (PMID 39670663, 2025). "As the tumorigenic role of PHGDH is being studied in patients with colorectal cancer (CRC), the therapeutic potential of PHGDH is being consistently suggested." (PMID 38945960, 2024). "PHGDH promotes tumorigenesis in many cancer types, such as pancreatic cancer, colorectal cancer, and liver cancer." (PMID 38816356, 2024). "In colorectal cancer, PHGDH undergoes monoubiquitylation by cullin 4A, which enhances its activity and promotes tumor cell migration and colorectal cancer metastasis through SAM-mediated histone methylation." (PMID 39207107, 2024). "STAU1 has been previously identified in colorectal cancer, whereas PHGDH protein has been identified in ovarian cancer." (PMID 37775701, 2023). "We demonstrated that PHGDH inhibition radiosensitized hypoxic human colorectal cancer cells while leaving intrinsic radiosensitivity unaffected." (PMID 36291844, 2022). "In conclusion, our results demonstrated that modulation of the de novo serine synthesis pathway, through inhibition of PHGDH, increases radioresponse in hypoxic colorectal cancer cells, while leaving the intrinsic radiosensitivity unaltered." (PMID 36291844, 2022). "Ultimately, DDB1-mediated PHGDH mono-ubiquitination drives colorectal cancer metastasis." (PMID 40598535, 2025). "In colorectal cancer, cMYC is a transcriptional activator of PHGDH." (PMID 40598535, 2025). "Additionally, analysis of the TCGA-CRC database confirmed that elevated PHGDH expression is significantly correlated with poor prognosis in colorectal cancer patients." (PMID 40368902, 2025). "Studies have shown that the circ_0062682/miR-940/PHGDH axis promotes serine metabolism and tumorigenesis in colorectal cancer, which may be a potential novel therapeutic target." (PMID 36699468, 2022). "Additionally, we evaluated whether PHGDH inhibition could improve radioresponse in human colorectal cancer cell lines in both aerobic and radiobiological relevant hypoxic conditions." (PMID 36291844, 2022). "The oleanolic acid analog LXH-3-71 functions as a novel molecular glue that covalently binds PHGDH at Cys281, promoting its ubiquitin-mediated degradation via the DDB1-CUL4 complex and thereby suppressing colorectal cancer stemness in preclinical models." (PMID 41614944, 2026). "In colorectal cancer cells, the novel molecular glue, LXH-3–71, covalently binds to PHGDH-C281, promoting the interaction between DDB1 and PHGDH." (PMID 40598535, 2025).
colorectal cancer (continued). "eIF3f can deubiquitinate and stabilize cMYC, thereby increasing cMYC‐mediated PHGDH transcription and promoting SSP to facilitate colorectal cancer development." (PMID 40598535, 2025). "In colorectal cancer (CRC) cells, phosphoglycerate dehydrogenase (PHGDH) catalyzes the initial step of de novo serine biosynthesis." (PMID 38535331, 2024). "For non-degradation pathways, PHGDH is monoubiquitinated to enhance its activity and promote the metabolite intermediate generation, thereby promoting colorectal cancer metastasis." (PMID 40598535, 2025). "The elimination of PHGDH induced by ubiquitin-proteasomal degradation can attenuate the stemness of colorectal cancer cells, and this phenomenon is not affected by the enzyme activity of PHGDH." (PMID 40598535, 2025). "Thus, EGF‐GSK3β‐FBXW7β axis regulates PHGDH expression, driving the Serine–Glycine–One–Carbon (SGOC) pathway to promote colorectal cancer progression." (PMID 40598535, 2025). "Conversely, another study found that the monoubiquitination of PHGDH does not mediate its degradation but promotes its activity, facilitating colorectal cancer metastasis." (PMID 39207107, 2024). "Using CRISPR-Cas9 we deleted PHGDH in HCT116 and DLD-1 colorectal cancer cells." (PMID 38066114, 2023).
lung adenocarcinoma (20 papers, 2019 to 2025). A carcinoma that arises from the lung and is characterized by the presence of malignant glandular epithelial cells. "Elevated PHGDH expression is evident in lung adenocarcinoma, a property associated with an unfavorable prognosis." (PMID 38945960, 2024). "In EGFR mutation-positive lung adenocarcinomas, downregulation of PHGDH or treatment with a PHGDH inhibitor increased ROS stress and DNA damage, ultimately sensitizing cells to receptor tyrosine kinase inhibitors (erlotinib)." (PMID 35011702, 2022). "PHGDH is overexpressed in triple negative breast cancer, lung adenocarcinoma, and other tumors, and is associated with a poor prognosis." (PMID 31235852, 2019). "Several solid tumors, including triple negative breast cancer, lung adenocarcinoma, and pancreatic cancer overexpress PHGDH, and inhibition of PHGDH can suppress cancer cell proliferation both in vitro and in PDX models." (PMID 36578934, 2022). "PHGDH acts on serine biosynthesis, and the inhibition of PHGDH was proposed to treat epidermal growth factor receptor-tyrosine kinase inhibitor (EGFR-TKI)-resistant lung adenocarcinoma." (PMID 33500332, 2021). "Collectively, PHGDH inhibitors are potential therapeutics for lung adenocarcinoma, but the optimal applications of such agents require further investigation." (PMID 33152171, 2021). "Although the clinical significance of mitochondrial stress responses in lung adenocarcinoma is not well understood, the expression of PHGDH in lung adenocarcinoma, which is regulated by NRF2‐mediated signaling, is associated with worse patient survival." (PMID 33152171, 2021). "In addition, for lung adenocarcinoma with low serine synthesis, the activation of mitochondrial stress responses might increase reliance on glycolytic serine synthesis and thus susceptibility to PHGDH inhibition." (PMID 33152171, 2021). "PHGDH is upregulated in erlotinib-resistant lung adenocarcinomas, likely due to the upregulation of glutathione and αKG synthesis as a cellular response to oxidative stress." (PMID 33511334, 2020). "The PHGDH level was also significantly increased in EGFR inhibitor erlotinib-resistant lung adenocarcinoma PC9ER4 and HCC827ER9 cells, which regulate the transcriptions of genes associated with DNA damage repair and nucleotide metabolism." (PMID 32226297, 2020). "Compared to the normal adjacent tissues, PHGDH expression is markedly and significantly elevated in lung adenocarcinoma and positively with poor prognosis." (PMID 32226297, 2020). "In lung adenocarcinoma, PHGDH contributes to resistance to the therapeutic agent erlotinib." (PMID 38945960, 2024). "Furthermore, phosphoglycerate dehydrogenase, the enzyme of serine biosynthesis, has potential therapeutic value in lung adenocarcinoma." (PMID 36389117, 2022). "Bioinformatics analysis of 720 lung adenocarcinoma patients and tissue microarray analysis of 75 lung adenocarcinoma (LUAD) and adjacent normal tissues revealed that PHGDH is a metabolic subtype of LUAD." (PMID 36699468, 2022). "Recently, it has been reported that PHGDH and TRIM29 are expressed in lung adenocarcinoma, and are indicators of poor prognosis." (PMID 35204409, 2022). "We further used NCT503 to block PHGDH, the rate‐limiting enzyme of glycolytic serine synthesis, and evaluated the role of this adaptive response in the proliferation of DNM1L‐KO lung adenocarcinoma cell lines." (PMID 33152171, 2021). "Additionally, we found increased protein expression of ATF4 and PHGDH, along with upregulated mRNA levels of PCK2, PHGDH, PSAT1, and PSPH, in DNM1L‐KO lung adenocarcinoma cell lines." (PMID 33152171, 2021). "During lung adenocarcinoma (LUAD) development, CBX4, a chromobox protein facilitates PHGDH transcription through interaction with GCN5, inducing increased histone acetylation on the PHGDH promoter, subsequently increasing serine biosynthesis and promoting LUAD proliferation." (PMID 40078876, 2025).
non-small cell lung carcinoma (20 papers, 2019 to 2025). A group of at least three distinct histological types of lung cancer, including non-small cell squamous cell carcinoma, adenocarcinoma, and large cell carcinoma. "SNP rs72699833 is located on chromosome 1 and is associated in cis with PHGDH, a gene involved in the metabolism of serine that is overexpressed in some subtypes of breast, cervical, colorectal and non-small-cell lung cancer, and in these diseases generally associated with a poorer outcome." (PMID 31806877, 2020). "To confirm this, we varied the cell NAD+/NADH ratio upon serine withdrawal and measured the serine synthesis rate of A549 non-small cell lung cancer cells, which transcriptionally upregulate the serine synthesis enzyme PHGDH." (PMID 40654753, 2025). "For example, when comparing the non-small cell lung cancer cells A549 and H1299, H1299 cells express less PHGDH protein than A549 cells but are more resistant to serine deprivation." (PMID 40654753, 2025). "PHGDH and PSAT1 are activated in non-small cell lung cancer, leading to changes in the metabolic pathways of serine." (PMID 36464703, 2022). "Human non-small cell lung cancer with high NRF2 protein expression displayed significantly higher expression of ATF4, PHGDH, PSAT1, and SHMT2, which was significantly related to poorer prognosis and higher tumor grade." (PMID 32226297, 2020). "Profiling of 79 non-small cell lung carcinoma (NSCLC) cell lines demonstrated a great heterogeneity in levels of serine and glycine, as well as in the expression of PHGDH." (PMID 32121279, 2020). "In non-small cell lung cancer (NSCLC) cells, a transcription factor NRF2 controls the expression of PHGDH and other key serine/glycine biosynthesis enzyme genes to support glutathione and nucleotide production." (PMID 30744688, 2019). "Additionally, PHGDH has been identified as a direct transcriptional target of ATF4, which was found to be transcriptionally activated by NRF2 in a non-small cell lung cancer model." (PMID 40102981, 2025). "Non-small cell lung cancer (NSCLC) and melanoma cancer models treated with vemurafenib activated serine/glycine synthesis as a mechanism of acquired resistance to targeted therapy, and the silencing of PHGDH reversed resistance to therapy." (PMID 40667288, 2025). "Furthermore, PHGDH, PSAT1, PSPH, and SHMT have been shown to be direct transcriptional targets of ATF4 which was transcriptionally activated by NRF2 in a non-small-cell lung cancer model." (PMID 31615983, 2019).